PRMT5 (protein arginine methyltransferase 5)
Diseases named in the same sentence as PRMT5 in open-access papers (continued):
Sharing a sentence is not in itself a finding about the gene and the disease.
cardiac hypertrophy (8 papers, 2020 to 2025). "Our results also show that cardiac hypertrophy is suppressed by PRMT5 deficiency specifically in periostin-positive cells." (PMID 38503742, 2024). "The differentially methylated genes CTSV & PRMT5 (ventricular hypertrophy and dilation) are linked to cardiovascular disease and of interest given the known association between impaired cerebral blood flow, cardiovascular disease, and AD." (PMID 33788842, 2021). "Although the HW/BW ratio was not considerably different between WT and PRMT5-TG mice under baseline conditions, pressure overload-induced cardiac hypertrophy was markedly exacerbated in the PRMT5-TG mice as compared to the WT mice." (PMID 40619438, 2025). "In contrast, our previous study showed that treatment with a PRMT5 inhibitor significantly suppressed pressure overload-induced pathological cardiac hypertrophy, myocardial fibrosis, and left ventricular systolic dysfunction." (PMID 40619438, 2025). "The gain-of-function of PRMT5 in cardiomyocytes exacerbates pressure overload-induced cardiac hypertrophy and left ventricular systolic dysfunction, at least partially, through p300 methylation and histone acetyltransferase activation." (PMID 40619438, 2025). "In this study, our experimental data suggest that PRMT5 in cardiomyocytes contributes to pathological cardiac hypertrophy through epigenetic activation of hypertrophic gene transcription." (PMID 40619438, 2025). "Since the overexpression of PRMT5 in cardiac myocytes accelerated cardiac systolic dysfunction, we assessed cardiac hypertrophy in mice." (PMID 40619438, 2025). "Our results reveal a novel molecular mechanism by which PRMT5 modulates pathological cardiac hypertrophy through histone acetylation." (PMID 40619438, 2025). "The gain-of-function of PRMT5 in cardiomyocytes accelerates pressure overload-induced cardiac hypertrophy and left ventricular systolic dysfunction through the regulation of p300 HAT activity." (PMID 40619438, 2025). "Here, we have demonstrated that PRMT5 overexpression in cardiomyocytes promotes pressure overload-induced myocardial hypertrophy." (PMID 40619438, 2025). "Cardiac-specific PRMT5 transgenic (PRMT5-TG) mice were generated to evaluate the gain-of-function of PRMT5 in cardiac hypertrophy and dysfunction in male mice undergoing TAC surgery." (PMID 40619438, 2025). "In line with these previous studies, our results indicate that PRMT5 in periostin-expressing fibroblasts plays a key role in the development of cardiac hypertrophy." (PMID 38503742, 2024). "PRMT5-regulated histone H4R3me2s promoted cardiac hypertrophy after impairment of isoprenaline-induced cardiac hypertrophy, but overexpression of PRMT5 reversed myocardial hypertrophy." (PMID 38584203, 2024). "Our results showed that the pharmacological inhibition of PRMT5 suppressed both cardiac hypertrophy and fibrosis in vivo." (PMID 38503742, 2024). "In cardiomyocytes, PRMT5 symmetrically dimethylates HoxA9 and inhibits HoxA9 expression, preventing binding to promoters and protecting cardiomyocytes from cardiac hypertrophy." (PMID 35855865, 2022). "PRMT5 (protein arginine methyltransferase 5), which usually is involved in the regulation of cardiac hypertrophy, decreases this cellular process through methylation of arginine in the histone 4 (H4R3me2)." (PMID 36523510, 2022). "Among all these PRMTs, PRMT5 is an arginine methyltransferase responsible for symmetric dimethylation, and is closely involved in cardiac hypertrophy according to our previous observations." (PMID 33424610, 2020). "The results are in line with those in vivo data, confirming that HoxA9 was upregulated while PRMT5 was downregulated in ISO-induced cardiac hypertrophy." (PMID 33424610, 2020). "Our preliminary studies showed that there were interactions between PRMT5 and HoxA9 in pathological cardiac hypertrophy and that HoxA9 was involved in the regulation of PRMT5 in cardiomyocyte hypertrophy." (PMID 33424610, 2020).
cardiac hypertrophy (continued). "In our previous study, treatment with a PRMT5 inhibitor EPZ015666 suppressed pressure overload-induced cardiac hypertrophy, indicating that PRMT5 in cardiomyocytes may accelerate the cardiac hypertrophy and systolic dysfunction caused by pressure overload." (PMID 40619438, 2025). "PRMT5 overexpression in hearts promoted pressure overload-induced myocardial hypertrophy." (PMID 40619438, 2025). "Moreover, treatment with a PRMT5 inhibitor also suppressed cardiac hypertrophy in mice after transverse aortic constriction (TAC) surgery." (PMID 40619438, 2025). "However, as the functional role of PRMT5 in cardiomyocytes remains to be fully elucidated in pathological cardiac hypertrophy and systolic dysfunction, this study aimed to clarify the gain-of-function of PRMT5 in cardiomyocytes." (PMID 40619438, 2025). "PRMT5 protects cardiomyocytes from hypertrophy by reducing GATA4 transcriptional activity, and activation of PRMT5 may be a potential therapeutic target for cardiac hypertrophy." (PMID 35855865, 2022). "The in vivo and in vitro observations that the expression of PRMT5 was decreased in cardiac hypertrophy, imply that repression of PRMT5 might contribute to the development of cardiac hypertrophy." (PMID 33424610, 2020). "Indeed, inhibition of PRMT5 facilitates cardiac hypertrophy through suppression of p300-mediated transcriptional activation of GATA4." (PMID 33424610, 2020). "Additionally, these results are in line with previous reports that PRMT5 protected against cardiac hypertrophy by methylating GATA4 to hamper p300-mediacted GATA acetylation, and by symmetric di-methylating Histone H4R3 via regulation of Filip1L/β-catenin." (PMID 33424610, 2020). "The present study revealed that PRMT5 was able to regulate Homebox (HOX) A9 in cardiac hypertrophy." (PMID 33424610, 2020). "The novel finding of our study is that PRMT5 could ameliorate cardiac hypertrophy via HoxA9." (PMID 33424610, 2020). "However, the gain-of-function of PRMT5 in pathological cardiac hypertrophy in vivo remains unknown." (PMID 40619438, 2025). "Although the functions in cardiac hypertrophy are still unknown, H4R3me2 does not seem to contribute to our conclusion that PRMT5 promotes hypertrophic gene transcription." (PMID 40619438, 2025). "While the baseline heart weight/body weight ratio was not changed by the knockout of Prmt5 in fibroblasts, TAC-induced cardiac hypertrophy was suppressed in the PostnMCM;Prmt5flox/flox mice." (PMID 38503742, 2024).
laryngeal carcinoma (8 papers, 2020 to 2024). Carcinoma that arises from the laryngeal epithelium. "Nevertheless, the mechanism underlying PRMT5- overexpression-induced EMT in laryngeal carcinoma remains unknown." (PMID 33060569, 2020). "In laryngeal carcinoma, PRMT5 regulates WNT4 expression, and PRMT5–WNT4 activates β-catenin to induce cadherin 2 (CDH2: also known as N-cadherin) and SNAIL expression, which is involved in EMT and promotes cell migration and lymph-node metastasis." (PMID 36980950, 2023). "We previously reported that PRMT5 is highly expressed in laryngeal carcinoma, of which the most malignant subtype of HNSC." (PMID 36878903, 2023). "Our previous work identified PRMT5 is highly expressed in laryngeal cancer cells, and involved in regulating protein arginine methylation." (PMID 36878903, 2023). "In conclusion, our present results identified the novel discovery that PRMT5 clinically and functionally participates in lymph-node metastasis and proliferation of laryngeal carcinoma by enhancing the Wnt/β-catenin pathway." (PMID 33060569, 2020). "Downregulated expression of PRMT-induced G1–S arrest indicated that suppression of PRMT5 inhibited laryngeal carcinoma proliferation by arresting the cell cycle in the G1 phase." (PMID 33060569, 2020). "Here we performed retrospective and prospective studies in clinical samples, and found that PRMT5 was abnormally upregulated in high-grade laryngeal carcinoma tissues." (PMID 33060569, 2020). "In conclusion, we first reported that increased expression of PRMT5 is an unfavorable prognostic marker in laryngeal carcinoma." (PMID 33060569, 2020). "In total, 2 × 106 laryngeal carcinoma cells (Tu212–PRMT5–Luc) that stably overexpressed PRMT5, generated by lentiviral transfection, and also stably expressed firefly luciferase, were inoculated into the footpads of nude mice." (PMID 33060569, 2020). "Further research is needed to clarify the exact mechanisms of PRMT5 in laryngeal carcinoma invasion–metastasis." (PMID 33060569, 2020). "We further demonstrated that ectopic expression of PRMT5 contributed to migration and invasion of laryngeal carcinoma cells (Tu686 and Tu212) in vitro and facilitated tumor metastasis in vivo." (PMID 33060569, 2020). "To investigate the potential effect of PRMT5 in laryngeal carcinoma, first, we examined the expression status of PRMT5 in laryngeal carcinoma cell lines, including Tu212, Tu686, M2e, M4e, and normal oral mucosa epithelial cell (NOK)." (PMID 33060569, 2020). "Taken together, these findings imply that PRMT5 promotes laryngeal carcinoma cell invasion and lymph-node metastasis in vivo." (PMID 33060569, 2020). "In this report, our findings show a correlation between PRMT5 overexpression and unfavorable prognosis of patients with laryngeal carcinoma." (PMID 33060569, 2020). "Here we identify protein arginine methyltransferase 5 (PRMT5) as a new metastasis-promoting factor in laryngeal carcinoma, and explore its underlying mechanism of action in regulating laryngeal cancer progression." (PMID 33060569, 2020). "Mechanistically, we demonstrated for the first time that PRMT5 promotes laryngeal carcinoma metastasis through activating the Wnt/β-catenin signaling pathway." (PMID 33060569, 2020). "In this study, we set out to reveal the contributions of PRMT5 in metastasis formation of laryngeal carcinoma via the Wnt/β-catenin pathway." (PMID 33060569, 2020). "The expression of PRMT5 was significantly higher in the laryngeal carcinoma tissues than that in the adjacent normal tissues." (PMID 33060569, 2020). "The results showed that the expression of PRMT5 was significantly higher in the laryngeal carcinoma tissues than that in the adjacent normal tissues." (PMID 33060569, 2020). "Functional assays revealed that PRMT5 promoted laryngeal carcinoma cell proliferation, migration, and invasive capacity in vitro, as well as lymph-node metastasis in vivo." (PMID 33060569, 2020).
laryngeal carcinoma (continued). "To gain insight into the mechanism of PRMT5-induced proliferation and metastasis of laryngeal carcinoma, we performed RNA-seq to identify transcriptional targets of PRMT5 knockdown in Tu686 and control cells." (PMID 33060569, 2020). "Next, we used the Wnt/β-catenin pathway-specific inhibitor XAV939 or activator LiCl to treat laryngeal carcinoma cells for 96 h; the PRMT5-mediated proliferation in Tu212 and Tu686 cells was dramatically suppressed or restarted, respectively." (PMID 33060569, 2020). "Next, to further elucidate the biological effects of PRMT5 on laryngeal carcinoma progression, western blotting and immunofluorescent staining were used to examine the effect of PRMT5 on the expression of EMT-related markers." (PMID 33060569, 2020). "In laryngeal cancer, PRMT5 promotes EMT through YAP1 signaling." (PMID 38444414, 2024). "Furthermore, in laryngeal carcinoma samples, PRMT5 expression was also shown to be positively correlated with β-catenin." (PMID 33060569, 2020). "Collectively, these results suggested that PRMT5 regulated proliferation via the Wnt4/β-catenin axis in laryngeal carcinoma, and the PRMT5/Wnt4 axis may serve as a potential therapeutic target for laryngeal carcinoma." (PMID 33060569, 2020). "Immunofluorescent staining results showed that the subcellular localization of β-catenin was mainly in the nucleus after overexpression of Wnt4 in PRMT5-depleted cells, which indicated that the β-catenin accumulation in the nucleus is necessary for PRMT5–Wnt4-induced laryngeal carcinoma metastasis." (PMID 33060569, 2020). "Taken together, these observations strongly suggest that PRMT5 might play a pivotal role in laryngeal carcinoma progression." (PMID 33060569, 2020). "Mechanistic explorations showed that PRMT5 could regulate tumorigenesis and metastasis of laryngeal carcinoma by activating the Wnt4/β-catenin signaling pathway." (PMID 33060569, 2020). "Moreover, a 123-case cohort from The Cancer Genome Atlas (TCGA) database showed that PRMT5 expression was upregulated in the laryngeal carcinoma with lymph-node metastasis compared with the tissues without lymph-node metastasis." (PMID 33060569, 2020). "To determine whether the Wnt/β-catenin pathway was activated by PRMT5 in laryngeal carcinoma cells, we then performed a luciferase experiment with TOP/FOP-Luc flash reporter assay." (PMID 33060569, 2020). "PRMT5 may serve as a novel prognostic marker and a therapeutic target for lymphatic metastasis of laryngeal carcinoma." (PMID 33060569, 2020). "Since tumor cell metastasis plays a pivotal role in tumor progression, we questioned whether PRMT5 was involved in the metastasis of laryngeal carcinoma cells." (PMID 33060569, 2020). "PRMT5 could be exhibited in the cytoplasm, the nuclei, or both of them, as well as in high-grade laryngeal carcinoma compared with lower-grade tissues with the most prominent expression in a nuclear distribution." (PMID 33060569, 2020). "Taken together, we put forward the hypothesis that PRMT5 may serve as a biomarker for lymph- node metastasis and unfavorable prognosis in laryngeal carcinoma." (PMID 33060569, 2020). "Together, these results further validated that PRMT5 may play an important role in the metastatic behavior of laryngeal carcinoma in vitro." (PMID 33060569, 2020). "We further investigated whether PRMT5-induced proliferation of laryngeal carcinoma cells and metastasis was Wnt4-dependent." (PMID 33060569, 2020). "We then studied the effect of PRMT5 on laryngeal carcinoma cell proliferation in vitro." (PMID 33060569, 2020). "The heterogeneity in the degree of PRMT5 expression in different-stage tumors prompted us to examine whether PRMT5 expression index correlated with laryngeal carcinoma patients’ survival." (PMID 33060569, 2020). "Besides, YY1 could transcriptionally activate PRMT5 and aid in proliferation and invasion in laryngeal cancer cells." (PMID 35658060, 2022).
laryngeal carcinoma (continued). "However, whether and how PRMT5 functions in lymph-node metastasis of laryngeal carcinoma remains unknown." (PMID 33060569, 2020). "PRMT5 may serve as a promising therapeutic target for highly invasive laryngeal carcinoma patients." (PMID 33060569, 2020). "To elucidate the effect of PRMT5 on the migration and mobility of laryngeal carcinoma cells, we performed in vitro wound-healing and Transwell assay, and found that PRMT5 overexpression increased migration and invasion of Tu212 cells, while PRMT5 knockdown in Tu686 cells had the opposite effect." (PMID 33060569, 2020). "In laryngeal cancer, YY1 (Yin Yang 1) binds to the promoter region of PRMT5, enhancing its transcription." (PMID 39255317, 2024). "In this study, we found that high PRMT5 expression was significantly correlated with worse overall survival and DFS of the patients, and showed an independent prognostic value in laryngeal carcinoma." (PMID 33060569, 2020). "Western blotting and IF analyses showed that the ectopic expression of PRMT5 induced EMT with downregulation of E-cadherin and upregulation of N-cadherin, snail, and MMP9 in laryngeal carcinoma cells." (PMID 33060569, 2020). "In this study, we demonstrated that PRMT5 is a coactivator to enhance the formation of β-catenin in the nucleus of laryngeal carcinoma cells, this signaling might be at least partly mediated by Wnt4, and the PRMT5/Wnt4 axis could be a new mechanism in laryngeal carcinoma development." (PMID 33060569, 2020). "Using both in vivo and in vitro models, we demonstrated that PRMT5 can facilitate EMT and lymph-node metastasis of laryngeal carcinoma cells via modulating the Wnt4/β-catenin pathway." (PMID 33060569, 2020). "The expression of PRMT5 was elevated in stages II and III laryngeal carcinoma tissues compared to stage I tissues." (PMID 33060569, 2020). "Recent studies have demonstrated that PRMT 1, a type I PRMT, functions as a positive regulator of YAP1 activity in chondrosarcoma, while PRMT5, a type II PRMT, promotes laryngeal cancer cell growth and its invasive capacity through the LATS2 and YAP1 signaling pathways." (PMID 38444414, 2024). "The PRMT5/WNT4 axis intensifies proliferation and lymph node metastasis of laryngeal carcinoma." (PMID 34476262, 2021). "Further, univariate and multivariate Cox regression analysis revealed that PRMT5, TNM stage, and lymph-node status may serve as an independent prognostic factor for overall survival of laryngeal carcinoma patients." (PMID 33060569, 2020). "Notably, the PRMT5 protein level was lower in normal tissues, but higher as disease severity progressed in laryngeal carcinoma tissues without lymph-node metastasis, regional lymph-node metastasis, and distant metastasis tumor tissues." (PMID 33060569, 2020). "The oncogenic role of protein arginine methyltransferase 5 (PRMT5) could activate the WNT4/β-catenin signaling pathway to induce laryngeal carcinoma cell proliferation, migration, and invasion in vitro, as well as lymph node metastasis in vivo, while silencing WNT4 could reverse the effect of PRMT5." (PMID 34642299, 2021).
myeloproliferative neoplasm (7 papers, 2017 to 2026). A clonal hematopoietic stem cell disorder, characterized by proliferation in the bone marrow of one or more of the myeloid (i.e., granulocytic, erythroid, megakaryocytic, and mast cell) lineages. "PRMT5 has been demonstrated to play a particularly critical role in leukemia and myeloproliferative neoplasms." (PMID 40181550, 2026). "Recently, JAK2V617F (a constitutively active JAK2 mutant) was shown to phosphorylates PRMT5 in myeloproliferative neoplasms." (PMID 28107179, 2017). "JAK2 V617F mutation could also interferes with epigenetic processes and recently the role of phosphorylate arginine methyltransferase PRMT5 in myeloproliferative neoplasm (MPN) pathogenesis was investigated." (PMID 35562964, 2022). "The two‐faced role of PRMT5 in blood cancer pathogenesis is exemplified by its role in myeloproliferative Neoplasms (MPN)." (PMID 40181550, 2026). "PRMT5 inhibition has also been studied in myeloproliferative neoplasms (MPN), especially in JAK2-mutated MPN with a decreased proliferation both in vitro and in patient samples." (PMID 36358861, 2022). "JAK2V617F-mediated phosphorylation of PRMT5 disrupted its interaction with MEP50, resulting in inhibition of its methyltransferase activity in myeloproliferative disease." (PMID 37173967, 2023). "PRMT5 inhibition was also reported to reduce the expression of E2F targets and alter the methylation status of E2F1 in JAK2V617F-mutant myeloproliferative neoplasms." (PMID 34531375, 2021). "JAK2V617F-dependent regulation of PRMT5 has provided an understanding of the molecular pathogenesis of myeloproliferative neoplasm; however, the regulatory mechanism for PRMT5 activity in normal physiological processes is yet to be unraveled." (PMID 32759981, 2020).